PICALM (phosphatidylinositol binding clathrin assembly protein)
Diseases named in the same sentence as PICALM in open-access papers (continued):
Sharing a sentence is not in itself a finding about the gene and the disease.
pulmonary fibrosis (1 paper, 2025). Chronic progressive interstitial lung disorder characterized by the replacement of the lung tissue by connective tissue, leading to progressive dyspnea, respiratory failure, or right heart failure. "Subsequently, cytoplasmic lnc668 promotes fibroblast-to-myofibroblast differentiation via PICALM to exacerbate pulmonary fibrosis." (PMID 40221424, 2025). "After nuclear export, lnc668 facilitated the translation and stability of its host gene PICALM to activate fibroblast-to-myofibroblast differentiation, leading to the aggravation of pulmonary fibrosis, which also depended on the phase separation of YTHDC1." (PMID 40221424, 2025). "After nuclear export, lnc668 facilitated the translation and stability of its host gene phosphatidylinositol-binding clathrin assembly protein to activate fibroblast-to-myofibroblast differentiation, leading to the aggravation of pulmonary fibrosis, which also depended on YTHDC1 phase separation." (PMID 40221424, 2025). "After nuclear export, cytoplasmic lnc668 promoted the translation and stability of PICALM mRNA, leading to increased levels of differentiation-related and fibrotic proteins, such as FAP, α-SMA, COL1A, COL3A, and VIM, thus contributing to the progression of pulmonary fibrosis." (PMID 40221424, 2025).
thyroid cancer (1 paper, 2024). "Control experiments validated the impact of SAHA on NIS, TSHR, AP2A1 and PICALM mRNA in thyroid cancer cells." (PMID 37921808, 2024). "The abrogation of PICALM significantly enhanced NIS expression and function in a similar manner to AP2α ablation, as well as blunting the induction of RAI uptake by CQ in thyroid cancer cells." (PMID 37921808, 2024).
cancer (16 papers, 2014 to 2024). A tumor composed of atypical neoplastic, often pleomorphic cells that invade other tissues. "Indeed, PICALM is listed in the Cancer Gene Census, a gene mutation database of cancers." (PMID 31407494, 2019). "The cancer-related genes BCL6, FANCC, PICALM and SGK1 were included among the target genes of the 64 TFBSs." (PMID 34316701, 2021). "Among these genes, PICALM (targeted by EP300), DDX6 (targeted by YY1) and LYL1 (targeted by LMO2) are reported on the COSMIC cancer gene list." (PMID 32850701, 2020). "The findings are that PICALM mediates the generation of Aβ peptide in CMs on DOX‐induced cardiotoxicity, highlighting the potential of PICALM as an effective intervention for cardiotoxicity during anti‐cancer therapy." (PMID 38935046, 2024).
neurodegenerative disease (7 papers, 2019 to 2025). A disorder of the central nervous system characterized by gradual and progressive loss of neural tissue and neurologic function. "AD and ALS are both neurodegenerative diseases, and PICALM has been proven to be the causative gene of AD." (PMID 33953791, 2021). "PICALM protein level is decreased in the affected brain areas of various tau-related neurodegenerative diseases, including AD, FTLD-tau-MAPT, corticobasal degeneration (CBD) and Lewy body dementia (LBD) diffuse type with tau pathology." (PMID 36552756, 2022). "VAMP3 has been implicated in several cellular processes including autophagy, through its role in autophagosome biogenesis and indirectly in neurodegenerative diseases such as AD, due to being regulated by the AD risk factor PICALM (Phosphatidylinositol binding clathrin-assembly protein)." (PMID 40619440, 2025). "A significant negative correlation was observed between PICALM protein level and hyperphosphorylated tau or autophagy initiation marker Beclin1 in the postmortem human frontal cortex of these neurodegenerative diseases." (PMID 36552756, 2022). "In HeLa cells, PICALM co-localizes with ATG16L1 on autophagic precursors, whereas in frontal cortices of patients with different neurodegenerative diseases, including AD, PICALM levels inversely correlate with those of the autophagic markers LC3-II and Beclin-1." (PMID 31159836, 2019).
tumor (5 papers, 2019 to 2024). "The results of fluorescence imaging showed that the fluorescence intensity of the shPICALM group was significantly lower than that of the shCtrl group, indicating that the tumor growth was slower after decreased the expression of PICALM (P < 0.05)." (PMID 35501863, 2022). "Firstly, the mRNA level of PICALM in human CRC primary tumor (n = 286) and normal tissues (n = 41) was analyzed from public databases." (PMID 35501863, 2022). "Five fusions found exclusively in tumour samples could be considered pathogenic (NFYG-TAL1, RIC3-TCRBC2, SLC35A3-HIAT1, PICALM MLLT10 and MLLT10-PICALM)." (PMID 30914738, 2019). "Importantly, PICALM silencing could inhibit the malignant phenotypes of CRC tumor cells by inhibiting proliferation and migration as well as promoting apoptosis." (PMID 35501863, 2022). "PICALM knockout was performed in MCF‐7 and NCI‐N87, followed by DOX treatment in both tumor cell lines." (PMID 38935046, 2024). "It was noted that phosphorylation of PKCδ, PICALM, and CDC37 were specifically enhanced in the tumor group, but few were identified in NT group." (PMID 36482371, 2022). "Then, we validated the expression of PICALM at the protein level by IHC staining of CRC tissue (n = 80) and normal tissues (n = 80), founding that the expression of PICALM in tumor tissues was significantly higher than that in normal tissues." (PMID 35501863, 2022). "Both CM presented proteins involved in proliferation of both tumor and non-tumor cells, of which CAPN1, CST1, LAMC2 and RANBP3 stood out in CM3D and GPC6, ILK, MAPK1, MIF and PICALM in CM2D." (PMID 34884877, 2021). "In addition, PICALM was required for the proliferation, apoptosis and migration of CRC tumor cells." (PMID 35501863, 2022). "Indeed, several pro-proliferation proteins were uniquely identified in CM2D such as PICALM, which positively regulate cell proliferation and GPC6, MAPK1, ILK and MIF, all involved in cell proliferation, migration and invasion, including that of tumor cells, cardiomyocytes and endothelial cells." (PMID 34884877, 2021).
infection (2 papers, 2019 to 2024). The state of being infected such as from the introduction of a foreign agent such as serum, vaccine, antigenic substance or organism. "PICALM is an intermediate mediator regulating the associated infection response." (PMID 37962454, 2024). "We therefore concluded that exosomal miR-155 inhibits EV-A71 infection via a PICALM-dependent mechanism." (PMID 31853228, 2019). "In conclusion, our experiments in SK-N-SH cells and EV-A71-infected mice show that exosomal miR-155 acts as a virus inhibitor, suppressing EV-A71 infection through targeting PICALM in vitro and in vivo." (PMID 31853228, 2019). "miR-155, which is significantly enriched in exosomes after EV-A71 infection, could effectively reduce the infection severity by repressing PICALM." (PMID 37962454, 2024). "We found that PICALM expression is down-regulated after EV-A71 infection (Figure." (PMID 31853228, 2019). "Moreover, exosomal miR-155 efficaciously inhibited EV-A71 infection by targeting phosphatidylinositol clathrin assembly protein (PICALM) in recipient cells." (PMID 31853228, 2019).
neurological disorders (1 paper, 2011). "This unique role for CALM, distinct from other clathrin adaptors, may explain the genetic association of the CALM/PICALM gene with neurological disorders." (PMID 22118466, 2011).
psychiatric disorder (1 paper, 2025). A disorder characterized by behavioral and/or psychological abnormalities, often accompanied by physical symptoms. "Twelve lead SNPs were located within 10 genes (BIN1, TMEM106B, AP001257.1, PICALM, SLC24A4, PVRL2, APOE, CLPTM1, CTB-179K24.3, and CASS4) for AD, and all three stress-related psychiatric disorders were identified using FUMA." (PMID 39975850, 2025).
PICALM also shares sentences with these, for which no sentence is quoted: cervical cancer (3 papers); breast carcinoma (2); Cognitive impairment (2); lung adenocarcinoma (2); acute lymphoblastic leukemia (1); asthma (1); bacterial infection (1); brain diseases (1); cataract (1); cognition (1); Down syndrome (1); hay fever (1); hematologic malignancies (1); immune disorder (1); liver cancer (1); lung squamous cell carcinoma (1); mental retardation (1); myeloid leukemia (1); Neurofibrillary tangles (1); non-small cell lung carcinoma (1); Obesity (1); ovarian carcinoma (1); preeclampsia (1); Senile plaques (1); stomach cancer (1); Stroke (1); T-cell acute lymphoblastic leukemia (1); vascular dementia (1).